BRD7 (bromodomain containing 7)
Diseases named in the same sentence as BRD7 in open-access papers (continued):
Sharing a sentence is not in itself a finding about the gene and the disease.
diabetes (3 papers, 2017 to 2024). "In the present study, we found that cardiac CHOP level was significantly increased in diabetic rats, BRD7 inhibition reduced diabetes‐induced CHOP expression." (PMID 27957794, 2017). "BRD7 inhibition effectively ameliorated diabetes‐induced CHOP expression (P < 0.05), ratio of Bax/Bcl‐2 (P < 0.05) and caspase‐3 activity (P < 0.05)." (PMID 27957794, 2017). "The expression of BRD7 was up‐regulated in the heart of diabetic rats, and inhibition of BRD7 had beneficial effects against diabetes‐induced heart damage." (PMID 27957794, 2017). "BRD7 suppressed Clusterin expression via modulating Clusterin promoter hypermethylation in an EZH2 dependent manner, thereby suppressing AMPK signaling to facilitate ferroptosis and induce diabetes-associated testicular damage." (PMID 38992588, 2024). "We have suggested that increased BRD7 expression may aggrandize diabetes or HG‐induced cardiomyocyte apoptosis, and BRD7 inhibition may have a protective effect on the myocardium in diabetes." (PMID 27957794, 2017). "In vivo findings showed that lack of BRD7 protected against diabetes-induced testicular damage and ferroptosis via increasing Clusterin expression and activating AMPK signaling." (PMID 38992588, 2024).
gastric cancer (3 papers, 2023 to 2025). A primary or metastatic malignant neoplasm involving the stomach.
glioma (3 papers, 2014 to 2022). A benign or malignant brain and spinal cord tumor that arises from glial cells (astrocytes, oligodendrocytes, ependymal cells). "Ectopic LRRC4 expression, 5-Aza-dC treatment, and BRD7-siRNA transfection each inhibited cell proliferation and induced cell cycle arrest at G0/G1 in glioma cells." (PMID 24404152, 2014). "We found that the expressions of miR-182, miR-381 or BRD7 proteins were inversely correlated with expression of LRRC4 in glioma tissues and normal brain tissues." (PMID 24404152, 2014). "In previous researches, we had focused on the effect of LRRC4 on the ERK/MAPK and PI-3K/AKT signaling pathways in gliomas, and transcriptional regulation of BRD7 expression in NPCs." (PMID 24404152, 2014). "In addition, there was a positive correlation found between expressions of miR-182 or miR-381 and BRD7 in all glioma tissues, and normal brain tissues." (PMID 24404152, 2014). "Thus, it was suggested that LNA-mediated miR-182 and miR-381 silencing down-regulated the expression of BRD7 by restoring LRRC4 expression in gliomas." (PMID 24404152, 2014). "But, the expression and function of BRD7 in gliomas have yet to be reported." (PMID 24404152, 2014). "We further found that the expression of miR-182 and miR-381 or BRD7 and LRRC4 were negatively correlated with the pathological progression of gliomas." (PMID 24404152, 2014). "To evaluate the relevance of the endogenous expressions of miR-182, miR-381, BRD7, and LRRC4, we assessed their expressions in human glioma tissues, as well as in normal brain tissues." (PMID 24404152, 2014). "ISH analysis of miR-182 and miR-381 and IHC analysis of BRD7 and LRRC4 showed that all 47 primary gliomas had elevated levels of miR-182, miR-381, and BRD7 (except for one case), and decreased levels of LRRC4 (except for two cases), as compared to levels detected in the 21 normal brain tissues." (PMID 24404152, 2014).
Glucose intolerance (3 papers, 2016 to 2023). Glucose intolerance (GI) can be defined as dysglycemia that comprises both prediabetes and diabetes. "The protein encoded by BRD7 acts as a coactivator/corepressor in various cellular processes and has been implicated in protection against glucose intolerance and insulin resistance, an important contributing factor to fatty liver development." (PMID 37859957, 2023). "On the other hand, upregulating BRD7 in the liver starting at an early age protects mice from gaining excessive weight and developing glucose intolerance and insulin resistance when challenged with a high-fat diet." (PMID 30926848, 2019).
Insulin resistance (3 papers, 2016 to 2023). Increased resistance towards insulin, that is, diminished effectiveness of insulin in reducing blood glucose levels. "Brd7 knockdown in combination with a HFD led to further disturbed glucose homoeostasis and insulin resistance." (PMID 27444544, 2016).
viral infection (3 papers, 2023 to 2024). "To examine the response of CD8+ T cell subsets of BRD7-sufficient and BRD7-deficient mice during virus infection, we infected Brd7fl/fl mice and Brd7ΔT mice with the influenza HKx31 strain and analyzed the CD8+ T cells in the spleen and lungs at the peak of the response (day 10 p.i.)." (PMID 38954484, 2024). "In the current study, we have identified a prominent role of BRD7 in regulating robust development of effector CD8+ T cells during acute virus infection, and it functions as a key determinant of the switch from naive T cells to effector T cells." (PMID 38954484, 2024). "BRD7 facilitates differentiation of CD8+ T cells into functional short-lived effector cells in response to viral infection and is required for viral clearance and host recovery." (PMID 38954484, 2024). "To further demonstrate the role of BRD7 in CD8+ T cell responses to other viral infection, we further utilized the LCMV infection model in our study, which initiates an acute infection." (PMID 38954484, 2024). "The findings highlight that EBV can control the biphasic life cycle by coordinating with host factors such as BRD7, ultimately providing insights into understanding the viral infection, pathogenesis, and BRD7-based therapeutics for EBV-associated BL." (PMID 36728436, 2023). "BRD7 was not required for the early activation and expansion of CD8+ T cells but was critical for effector differentiation of CD8+ T cells and pathogen clearance during acute viral infection." (PMID 38954484, 2024).
autoimmune disease (2 papers, 2023 to 2024). A disorder resulting from loss of function or tissue destruction of an organ or multiple organs, arising from humoral or cellular immune responses of the individual to their own tissue constituents. "This is the first study to identify a connection between the gene BRD7 and AITD; moreover, published studies on the correlation between BRD7 and other autoimmune disorders are scarce, and more study is urgently needed." (PMID 37197658, 2023).
Azoospermia (2 papers, 2016 to 2021). Absence of any measurable level of sperm,whereby spermatozoa cannot be observed even after centrifugation of the semen pellet. "A total of six heterozygous variants were detected in the coding and splicing regions of the BRD7 gene in patients with azoospermia." (PMID 34470615, 2021). "Our studies demonstrate the critical role of BRD7 in spermatogenesis and male fertility, suggesting that BRD7 may be a promising target for the diagnosis and treatment of human idiopathic azoospermia patients." (PMID 26878912, 2016). "Furthermore, no or lower expression of BRD7 was detected in the testes of azoospermia patients exhibiting spermatogenesis arrest than that in control group." (PMID 26878912, 2016). "Moreover, idiopathic azoospermia was characterized by no or low BRD7 expression." (PMID 26878912, 2016).
colon cancer (2 papers, 2017 to 2022). "BRD7 expression was found to be suppressed in endothelial cells (EC) isolated from human colon tumors as compared to isolated EC from normal colon tissue." (PMID 28951988, 2017). "In addition, mining The Protein Atlas data also revealed a reduction in BRD7 protein expression in colon tumors as compared to normal colon." (PMID 28951988, 2017). "Vascular BRD7 expression was virtually absent in colon tumor sections." (PMID 28951988, 2017).
colorectal tumor (2 papers, 2017 to 2022). "Not only is BRD7 mRNA specifically downregulated in TEC, global BRD7 mRNA expression was reduced in a panel of colorectal tumors compared to normal colon, confirming previous reports." (PMID 28951988, 2017). "Consistent with a role for BRD7 as pro-tumorigenic in some contexts, a different study found BRD7 stabilizes MYC and promotes colorectal tumor growth." (PMID 35323214, 2022).
infertile (2 papers, 2020 to 2021). "To explore the association of BRD7 with human spermatogenic failure, we comprehensively investigated the influence of rare and common variants of BRD7 on the spermatogenic phenotype in 315 infertile patients with AZ or OZ and 995 males with NZ in the present study." (PMID 34470615, 2021). "Moreover, mice knockout of BRD7 resulted in infertility and spermatogenesis defects." (PMID 32111017, 2020).
lung adenocarcinoma (2 papers, 2020 to 2024). A carcinoma that arises from the lung and is characterized by the presence of malignant glandular epithelial cells. "BRD7 expression is decreased in NSCLC, and low levels of BRD7 are associated with reduced survival rates in lung adenocarcinoma patients." (PMID 32992509, 2020).
lymph node metastasis (2 papers, 2011 to 2025). "Positive BRD7 expression in the lymph node metastasis group was significantly higher than that in the non-lymph node metastasis group." (PMID 22008115, 2011).
oral cancer (2 papers, 2022). "In the nucleus of cancer cells, HAR1A functioned upstream of the signaling pathway, and knockdown of HAR1A promoted ALPK1 expression and downregulated myosin IIA and BRD7, leading to inflammation and oral cancer progression." (PMID 36139553, 2022). "HAR1A acted as a tumor suppressor for oral cancer by regulating the ALPK1/BRD7/myosin IIA axis in oral cancer." (PMID 35740511, 2022).
triple-negative breast carcinoma (2 papers, 2012 to 2021). An invasive breast carcinoma which is negative for expression of estrogen receptor (ER), progesterone receptor (PR), and human epidermal growth factor receptor 2 (HER2). "In the present study, we scanned the whole coding regions of BRCA1, BRCA2, PALB2 and BRD7 in order to investigate the relative contributions of germ-line mutations in these genes to triple-negative breast cancer in a hospital-based series of German patients." (PMID 23110154, 2012). "We investigated a hospital-based series of 40 consecutive patients with triple-negative breast cancer for mutations in the whole coding sequences of BRCA1 and BRCA2 as well as in the two genes PALB2 and BRD7, which encode interaction partners of the BRCA1 protein." (PMID 23110154, 2012).
acute leukemia (1 paper, 2022). A clonal (malignant) hematopoietic disorder with an acute onset, affecting the bone marrow and the peripheral blood. "Nevertheless, upregulation of BRD7 was observed in blood cells derived from patients with acute leukemia." (PMID 36291090, 2022).
adenosquamous carcinoma (1 paper, 2018). A carcinoma composed of malignant glandular cells and malignant squamous cells. "The expression of AGR2 and BRD7 was cell type-dependent; AGR2 was more highly expressed in adeno/adenosquamous carcinoma, and BRD 7 expression was more prominent in squamous cell carcinoma (p < 0.001 and p = 0.004, respectively)." (PMID 30406031, 2018).
astrocytomas (1 paper, 2014). "More importantly, we also found that miR-182, miR-381 and BRD7 were inversely correlated with LRRC4 in astrocytomas of various pathological grades, and the extent of correlation increased from WHO grade I to IV." (PMID 24404152, 2014).
bladder cancer (1 paper, 2025). "The loss of the bromodomain leads to cancer sensitivity to PARPi and CPT, while small molecules containing bromodomains, such as BRD7, occur mutations in cancer types such as bladder cancer, which may indicate that bromodomain inhibitors are effective for bladder cancer treatment." (PMID 39779467, 2025).
colitis (1 paper, 2021). Inflammation of the colon. "In this study, we further employed a well-established azoxymethane (AOM)/DSS model of colitis-associated cancer with BRD7 knockout mice and determined the functional role of BRD7 in colitis-associated CRC." (PMID 34109174, 2021). "Taken together, all of the findings above revealed that BRD7+/+ mice are highly susceptible to colitis-associated CRC and that BRD7 plays a crucial cancer-promoting role in colorectal carcinogenesis in mice." (PMID 34109174, 2021). "Moreover, consistent with its tumor-suppressive role, BRD7 exerts an anti-inflammatory effect in the early stage of dextran sodium sulfate (DSS)-induced colitis in a BRD7 knockout mouse model." (PMID 34109174, 2021).
Globozoospermia (1 paper, 2016). Any structural anomaly of the acrosome resulting in a round sperm head. "In our study, defective acrosome formation in BRD7−/− mice was observed in abnormal spermatids with a globozoospermia-like shape, which indicates that abnormalities in acrosome formation influences the formation of spermatid heads in BRD7−/− mice." (PMID 26878912, 2016).
hemochromatosis (1 paper, 2018). A disorder of iron metabolism characterized by a triad of HEMOSIDEROSIS; LIVER CIRRHOSIS; and DIABETES MELLITUS. "Examples are mitogen-activated protein kinase (MAPK)/RAS family members (HRAS and NRAS), hemochromatosis (HFE), BRD7, ATM, vimentin (VIM), which are upregulated in poorly differentiated cell lines and in human HCC datasets." (PMID 30176945, 2018).
latent infection (1 paper, 2023). "The results implied that BRD7 expression is associated with EBV latent infection." (PMID 36728436, 2023). "This study identified bromodomain-containing protein 7 (BRD7) as a crucial host protein in EBV latent infection." (PMID 36728436, 2023). "The data indicate that EBV has established roles by colocalizing with BRD7 at the viral genome for its advantage during latent infection." (PMID 36728436, 2023). "The EBV genome persists in infected host cells as extrachromosomal episomes and is subject to chromatin-mediated regulation, raising our question of whether BRD7 may regulate the viral genomes in latent infection." (PMID 36728436, 2023). "Furthermore, we analyzed the RNA level of BRD7 in latent infection from the database established by Wolfgang Hammerschmidt and his colleagues, and the result showed that BRD7 was upregulated in B cells throughout the time points after EBV infection." (PMID 36728436, 2023). "Therefore, regulating the c-Myc transcriptional level accompanied by the change of BRD7 expression might depend on EBV latent infection." (PMID 36728436, 2023). "The enrichment of BRD7 at oriP and Qp was analyzed and showed that BRD7 binds to these two regions in the EBV genome, suggesting that BRD7 at these sites is important for the maintenance of viral episomal genomes during latent infection." (PMID 36728436, 2023). "This raised the question of whether BRD7, highly induced during EBV latent infection, could be a key regulator of the viral lytic program." (PMID 36728436, 2023). "We further focused on the direct DNA binding property of BRD7 to identify a category of differentially regulated regions in the host chromatin and viral genome and further substantiated these changes through the coordination with c-Myc and EBNA1 during EBV latent infection in BL cells." (PMID 36728436, 2023).
leukemia (1 paper, 2022). A malignant (clonal) hematologic disorder, involving hematopoietic stem cells and characterized by the presence of primitive or atypical myeloid or lymphoid cells in the bone marrow and the blood.
liver cirrhosis (1 paper, 2016). "The correlation analysis revealed that decreased BRD7 expression was significantly associated with TNM stage (P = 0.002) and tumor size (P = 0.008), but not with gender, age, HBsAg, serum AFP, liver cirrhosis, histological differentiation, tumor capsule or tumor number." (PMID 26919247, 2016).
liver fibrosis (1 paper, 2022).
Myocardial fibrosis (1 paper, 2017). "In addition, we found that BRD7 inhibition ameliorated myocyte hypertrophy, myocardial fibrosis and cardiac dysfunction in DM rats." (PMID 27957794, 2017).
primary immunodeficiency (1 paper, 2023). "Meanwhile, it has been demonstrated that low expression of BRD7 in the disease activates the primary immunodeficiency pathway." (PMID 37378023, 2023).
sarcoma (1 paper, 2022). A usually aggressive malignant neoplasm of the soft tissue or bone. "In conclusion, PBAF complexes (potentially without BRD7) bind stronger to chromatin than the other two subtypes in FET sarcoma cells and FET oncoproteins have similar binding profiles as SWI/SNF components that are distinct from normal FET proteins." (PMID 35182012, 2022).
type 1 diabetic (1 paper, 2017). "In the present study, we found that BRD7 expression was increased in the type 1 diabetic rat heart and in HG‐treated H9c2 cardiomyoblasts." (PMID 27957794, 2017). "In vivo, we established a type 1 diabetic rat model by injecting a high‐dose streptozotocin (STZ), and lentivirus‐mediated short hairpin RNA (shRNA) was used to inhibit BRD7 expression." (PMID 27957794, 2017).